U3 (Small nucleolar RNA U3 )
Synonyms: LOC124901861
Gene: Small nucleolar RNA gene on chromosome 7 (107,999,791 to 107,999,982, reverse strand). Ensembl gene ENSG00000238297.
Gene Ontology:
Biological process: RNA processing
Cellular component: nucleolus
Homologues: Orthologues: chimpanzee U3 (98% identical), macaque U3 (91% identical), rabbit U3 (62% identical), rat LOC120102769 (60% identical). Paralogues in human: SNORD3P1 (82% identical), U3 (80% identical), SNORD3E (78% identical), U3 (78% identical), U3 (77% identical), U3 (76% identical), SNORD3H (75% identical), U3 (75% identical), SNORD3G (74% identical), U3 (74% identical), U3 (73% identical), SNORD3D (73% identical), and 13 more.